VCAM1 (vascular cell adhesion molecule 1)
Diseases named in the same sentence as VCAM1 in open-access papers (continued):
Sharing a sentence is not in itself a finding about the gene and the disease.
endothelial dysfunction (continued). "The combination therapy reverses the diabetes induced endothelial dysfunction through downregulation of the expression of VCAM-1 levels (abdominal and thoracic aortae) as compared to that in diabetic control." (PMID 36496468, 2022). "For endothelial dysfunction measured using Ach-induced iontophoresis, eGFR's indirect effect mediated by iPTH and VCAM-1 was significant, as opposed to eGFR's direct effect, and iPTH significantly mediated the effect of VCAM-1 on endothelial dysfunction." (PMID 35903313, 2022). "Consistent with this, L-NAME administration did not alter mesenteric artery expression of the enzyme responsible for production of nitric oxide Nos3, the endothelial dysfunction marker Vcam-1, or the receptors for vasoconstrictor endothelin-1, Ednra and Ednrb." (PMID 36260752, 2022). "We also explored levels of circulating vascular cell adhesion molecule-1 (sVCAM-1) in Morquio A patients, which is indicative of endothelial dysfunction." (PMID 35620518, 2022). "Consumption of a single high-fat meal rich in saturated fatty acids can induce endothelial dysfunction in otherwise healthy subjects, as evidenced by the related increased concentrations of VCAM-1, ICAM-1, IL-6, IL-18, and TNF-α." (PMID 35268723, 2022). "In a similar study, proton pump inhibitors were shown to be able to ameliorate TNF-α-induced endothelial dysfunction of HUVECs and uterine microvascular cells, by blocking VCAM-1 expression, leukocytes adhesion to endothelium and irregular tube formation." (PMID 33919808, 2021). "Following endothelial dysfunction, adhesion molecules (e.g., VCAM-1, ICAM-1 and E-selectin) and chemokines (e.g., MCP-1) trigger the recruitment of monocytes to the aortic intima." (PMID 34769040, 2021). "In this study, melatonin also decreased mRNA expression in the aorta of endothelial dysfunction markers including vascular cell adhesion molecule-1 (VCAM-1), ICAM-1 and E-selectin." (PMID 33802558, 2021). "ELISA kits were used to detect the levels of endothelial dysfunction (ED) markers, including vascular cell adhesion molecule 1 (VCAM-1), intercellular adhesion molecule 1 (ICAM-1) and E-selectin." (PMID 33546604, 2021). "Vcam1 mRNA expression leveled higher in all exposure groups from the beginning (almost similar to endothelial dysfunction that was also present from the beginning of noise exposure and not changed during prolonged exposure." (PMID 35174211, 2021). "Log-IS and log-PCS also correlated with markers of endothelial dysfunction (log-IS and log-VCAM-1, r = 0.55, p < 0.0001; IS and log-vWF, r = 0.30, p = 0.0005; log-PCS and log-VCAM-1, r = 0.52, p < 0.0001; log-PCS and log-vWF, r = 0.40, p < 0.0001)." (PMID 33423673, 2021). "CM has a preventive effect against endothelial dysfunction by lowering inflammatory response (through VCAM-1, ICAM-1 expression regression) and reducing caspase-mediated apoptosis." (PMID 33627181, 2021). "Fifth, the expression of adhesion molecules such as P-selectin, E-selectin, ICAM-1, and VCAM-1 is increased; these are all markers of endothelial dysfunction, and can serve as receptors for leukocytes (monocytes, neutrophils, and lymphocytes)." (PMID 34200975, 2021). "Biomarkers of endothelial dysfunction, namely vascular cell adhesion molecule 1 (VCAM-1) and intercellular adhesion molecule 1 (ICAM-1), were evaluated in the aorta." (PMID 34940528, 2021). "It has been well documented that biomarkers of endothelial dysfunction include vascular cell adhesion molecule (VCAM-1), intercellular adhesion molecule (ICAM-1) and endothelial leukocyte adhesion molecule (ELAM-1)." (PMID 33924982, 2021). "Glycocalyx damage correlated with markers of endothelial dysfunction (log-hyaluronan and log-VCAM-1: r = 0.64, p < 0.001) and levels of uraemic toxins (log-hyaluronan and log-indoxyl sulphate: r = 0.48, p < 0.001)." (PMID 33423673, 2021).
endothelial dysfunction (continued). "In porcine coronary artery cultured endothelial cells, high glucose increased endothelial dysfunction markers, oxidative stress, and vascular cell adhesion molecule 1 (VCAM-1), and reduced NOS expression." (PMID 34884494, 2021). "Endothelial dysfunction is characterized by the increased expression of adhesion molecules, such as vascular cell adhesion molecule-1 (VCAM-1) and intercellular adhesion molecule-1 (ICAM-1), allowing the accumulation of monocytes in the subendothelial matrix." (PMID 34201484, 2021). "The anthropometric and blood indices before and after exercise were recorded and compared, and the endothelial dysfunction was evaluated by examining the levels of markers, including VCAM-1, ICAM-1, and E-selectin, using an ELISA assay." (PMID 34123418, 2021). "Endothelin 1 (ET-1) and vascular cell adhesion molecule 1 (VCAM-1) are markers of endothelial dysfunction that are also elevated in preeclampsia." (PMID 33919808, 2021). "Specifically, the miR-221/222 cluster suppresses endothelial production of matrix metalloproteinases (MMPs), several key adhesion modulators, vascular cell adhesion molecule-1 (VCAM-1), integrin-β3), and eNOS, promoting endothelial dysfunction." (PMID 34201562, 2021). "On other hand, miR-126 or miR-223 that are linked to arterial thrombosis target proteins that cause endothelial dysfunction, alternation of lipid metabolism or trigger inflammation and target ICAM-1, VCAM-1, IL-6 or IL-8." (PMID 32443696, 2020). "Recent research investigating adipocytes-derived EVs, found that these inflammatory EVs upregulate VCAM-1 production in vascular endothelial cells which stimulates exaggerated leukocyte attachment, promoting inflammation and endothelial dysfunction." (PMID 33042016, 2020). "The incubation of endothelial cells in vitro with MPs from obese rats enhanced the expression of vascular cell adhesion molecule 1 (VCAM-1) and increased oxidative stress indicating that MPs from insulin resistant animals induced endothelial dysfunction." (PMID 30915196, 2019). "Our data not only suggest that ER stress induces transendothelial migration of leukocytes via upregulation of Icam1, Vcam1 and Ccl2 but it also involves O-glycosylation events suggesting a key role for PTMs in endothelial dysfunction." (PMID 31346222, 2019). "The presence of inflammation was also supported by the increased expression in the myocardium of mRNA coding for Il1b and for Vcam1, an adhesion molecule responsible for the adhesion of leukocytes to the endothelium, suggesting endothelial dysfunction." (PMID 31393963, 2019). "We next investigated the effects of silencing GATA2 on markers of endothelial dysfunction, VCAM-1 and ET-1." (PMID 30659233, 2019). "The administration of either cytotrophoblast conditioned media, or TNFα to HUVECs significantly increased endothelial dysfunction marker, VCAM-1 expression (p < 0.0001)." (PMID 30659233, 2019). "Several studies have demonstrated changes in the levels of cell adhesion molecules such as ICAM1, VCAM1 and selectins in response to oxidative stress in endothelial cells which result in the progression of endothelial dysfunction." (PMID 31547324, 2019). "TNF-α was used to induce endothelial dysfunction in primary HUVECs and the expression of vascular cell adhesion molecule (VCAM-1; a marker of endothelial dysfunction) assessed." (PMID 29466360, 2018). "Increased circulating VCAM-1 levels are observed in inflammatory conditions as well as with endothelial dysfunction." (PMID 30383759, 2018). "The present study was aimed at determining plasma levels of ICAM-1, VCAM-1 and E-Selectin as markers of endothelial dysfunction in SCD patients in steady state, complications and controls." (PMID 29690499, 2018).
endothelial dysfunction (continued). "A rise in the serum levels of cellular adhesion molecules, intercellular adhesion molecule 1 (ICAM-1), and vascular cell adhesion molecule 1 (VCAM-1) as specific markers of endothelial dysfunction indicates an impaired endothelial function." (PMID 31011351, 2018). "The current study aimed to determine plasma levels of ICAM-1, VCAM-1 and E-Selectin as markers of endothelial dysfunction in SCD patients in steady state, complications and controls." (PMID 29690499, 2018). "Endothelial cell activation accompanies endothelial dysfunction, and is characterized by increased expression of adhesion molecules such as vascular cell adhesion molecule-1 (VCAM-1) and intercellular adhesion molecule-1 (ICAM-1)." (PMID 29337890, 2018). "VCAM-1 is a cellular adhesion molecule, and is a biomarker of endothelial dysfunction, and interestingly it was lower (p<0.05) in the LGA group, compared to the other groups." (PMID 30383759, 2018). "This is because VCAM-1, ICAM-1, and E-Selectin are all markers of endothelial dysfunction, and have been implicated in the pathology of SCD." (PMID 29690499, 2018). "Other potential serum biomarkers related to the endothelial dysfunction and inflammation are the nitric oxide, the soluble vascular cell adhesion molecule-1, the high-sensitivity C-reactive protein, the tumour necrosis factor-α, the IL-6 and the P-selectin." (PMID 28933368, 2017). "Dh404 significantly attenuated endothelial dysfunction in diabetic Akita mice characterized by reduced contraction in response to phenylephrine and the downregulation of inflammatory genes (VCAM-1, ICAM-1, p65, IL-1β) and pro-oxidant genes (Nox1 and Nox2)." (PMID 28253885, 2017). "The high expression of adhesion molecules, such as ICAM-1 and VCAM-1, leading to an abnormal increase in adhesion ability onto endothelial cell surface, is an important feature of endothelial dysfunction." (PMID 28798687, 2017). "Endothelial dysfunction was induced in HUVECs using TNFα, increasing expression of cell adhesion molecule VCAM1 and adhesion of peripheral blood mononuclear cells, both of which were increased further by resveratrol." (PMID 28500309, 2017). "We further evaluated the results of clopidogrel treatment on soluble VCAM1 levels as a marker of endothelial dysfunction/injury." (PMID 27188755, 2016). "Accordingly, bothautoantibodies induced upregulation of MCP-1, TF, and VCAM-1, and downregulationof eNOS, relevant markers of endothelial dysfunction, and potential targets ofthe miRNAs evaluated." (PMID 27502756, 2016). "Although several studies of the biomarkers of endothelial dysfunction have been done in patients with T2DM and most of them have demonstrated increased concentration of E-selectin, ICAM-1, and VCAM-1 data about the endothelial dysfunction in MCI are poor." (PMID 26167502, 2015). "The effects of CIT were linked with the strong upregulation of aortic inflammation (ICAM-1 and VCAM-1) and endothelial dysfunction in the atherosclerotic model." (PMID 25933220, 2015). "VCAM-1 expression (a biomarker of endothelial dysfunction) was also induced by MRTF-A/B downregulation, although these effects were modest compared to those observed after TNF−α or LPS stimulation." (PMID 26024305, 2015). "ICAM-1 and VCAM-1 expression is up regulated during endothelial-dysfunction at postmenopause, a phenomenon also influenced by estrogen receptors (ERs) SNPs, contributing to systemic inflammation and endothelial damage." (PMID 25993480, 2015). "ICAM-1 and VCAM-1 are important markers of endothelial dysfunction that have been demonstrated to play important roles in the development of diabetic retinopathy." (PMID 25287126, 2014). "Axl transfection significantly reversed HG-induced Akt phosphorylation, VCAM-1 expression and endothelial dysfunction." (PMID 24572151, 2014). "ICAM-1, VCAM-1, and ET-1 are important markers of endothelial dysfunction that have been demonstrated to play important roles in the development of DRP." (PMID 24688225, 2014).
endothelial dysfunction (continued). "Circulating sICAM-1 (intracellular-adhesion-molecule-1), sVCAM-1 (vascular-cell-adhesion-molecule-1) and sE-selectin, representing biomarkers of endothelial dysfunction were assessed at baseline and annually over five years." (PMID 25281032, 2014). "Circulating endothelial dysfunction biomarkers included soluble intercellular adhesion molecule-1 (sICAM-1), vascular cell adhesion molecule-1 (sVCAM-1) and soluble E-selectin (sE-selectin)." (PMID 24465662, 2014). "The increased expression of VCAM-1 is a marker of vascular inflammation, vascular permeability and endothelial dysfunction." (PMID 25184237, 2014). "Increased VCAM-1, as discussed in the literature, is a marker of vascular inflammation, vascular permeability, and endothelial dysfunction." (PMID 23970958, 2013). "Endothelial dysfunction indicated by elevation of vWF, ICAM-1, or VCAM-1 was associated with significantly higher AF than in diabetic patients with normal levels of these parameters." (PMID 23671885, 2013). "Endothelial dysfunction in FFHR causes an increase in the expression of NF-κB and AP-1 and the posttranscriptional product VCAM-1." (PMID 23970958, 2013). "Endothelial dysfunction was also assessed by the expression of adhesion molecules, such as ICAM-1 and VCAM-1, which have been associated with the development of CVD in diabetic patients." (PMID 23497124, 2013). "Our study revealed that plasma Gas6 levels were not only negatively correlated with the endothelial dysfunction markers E-selectin and VCAM-1 but also negatively correlated with the predicted mortality rate calculated from the EuroSCORE II system." (PMID 24236135, 2013). "For instance, PM2.5 exposure has been associated with elevated blood levels of two markers of endothelial dysfunction—intercellular adhesion molecule-1 (ICAM-1) and vascular cell adhesion molecule-1 (VCAM-1) —which are also shown to increase in preeclampsia." (PMID 24021707, 2013). "The increased expression of VCAM-1, as discussed in the literature, is a marker of vascular inflammation, vascular permeability, and endothelial dysfunction." (PMID 23365721, 2013). "The expression of adhesion markers such as vascular cell adhesion molecule-1 and platelet endothelial cell adhesion molecule-1 are increased in the renal vasculature indicating initiation of endothelial dysfunction." (PMID 23300650, 2012). "Elevated levels of markers of endothelial dysfunction (E-selectin, vascular cell adhesion molecule 1(VCAM-1)) have been determined in the plasma of older subjects with late onset AD and vascular dementia." (PMID 21439035, 2011). "Endothelial dysfunction biomarkers including von Willebrand factor, VCAM-1 and thrombomodulin, as well as the soluble form of CX3CL1 were measured by enzyme-linked immunosorbent assays (ELISA)." (PMID 19587779, 2009). "We explored these polymorphisms in a case-control study and evaluated endothelial dysfunction by measuring several biomarkers including VWF, VCAM-1 and thrombomodulin, as well as the soluble form of CX3CL1." (PMID 19587779, 2009). "We found that the biomarkers of endothelial dysfunction VCAM-1, ICAM-1 and ELAM-1 were higher in 74 RA patients than in 80 healthy control individuals." (PMID 15899050, 2005). "In univariate analysis, all three biomarkers of endothelial dysfunction (VCAM-1, ICAM-1 and ECAM-1) were higher in patients than in control individuals." (PMID 15899050, 2005). "Functional studies revealed that MALAT1 depletion increased, while MALAT1 overexpression decreased, the endothelial dysfunction markers endothelin-1 (ET-1) and vascular cell adhesion molecule-1 (VCAM1), indicating a protective role of MALAT1 in maintaining endothelial homeostasis." (PMID 41597229, 2026). "Additionally, vascular cell adhesion molecule 1 (VCAM‐1), which is abundantly expressed on activated endothelial cells, serves as a marker of endothelial dysfunction." (PMID 41310943, 2026).
endothelial dysfunction (continued). "Furthermore, TGF-β has been shown to induce the expression of pro-fibrotic and pro-inflammatory markers, such as VCAM-1 and Collagen I, which are upregulated in Abcb8ECKO and are known to contribute to vascular stiffness and endothelial dysfunction." (PMID 41252867, 2025). "Various markers of endothelial injury have been investigated in CAR-T cell recipients, including markers of complement activation, such as soluble C5b-9, endothelial dysfunction (angiopoietin-2, VCAM1, ICAM-1), inflammation, and thrombosis (von Willebrand antigen, ADAMTS13, thrombomodulin)." (PMID 40940973, 2025). "VCAM-1 promotes leukocyte adhesion and endothelial activation, while iNOS contributes to oxidative stress and impaired vasodilation, and both are established contributors to endothelial dysfunction." (PMID 40725048, 2025). "Moreover, cytokine-induced endothelial dysfunction results in increased vascular permeability, expression of adhesion molecules (VCAM-1, ICAM-1), and reduced NO bioavailability, thereby promoting a pro-atherogenic state." (PMID 40227756, 2025). "Finally, P5P reversed the beneficial impact of 1,25-D3 on neurological injury and endothelial dysfunction by modifying the expression of inflammatory and vascular protection factor-associated proteins such as GLP-1R, VEGF-α, e-NOS, ICAM-1, and VCAM-1." (PMID 40224490, 2025). "Acute exposure to ambient PM2.5 pollution may lead to a substantial increase in key markers of endothelial function, such as ICAM-1, VCAM-1, and selectins indicating potential endothelial dysfunction as a result of exposure to ambient air pollution." (PMID 40149705, 2025). "This is supported by studies on vascular and endothelial dysfunction markers, such as CD93 and VCAM-1, which have been associated with both nephropathy and cardiopathy—further reinforcing the broader implications of vascular anomalies in hypertension development." (PMID 40004797, 2025). "This activation is particularly pronounced in severe COVID-19 cases, leading to elevated levels of soluble ICAM-1 (intercellular adhesion molecule 1) and VCAM-1 (vascular cell adhesion molecule 1), which contribute to endothelial dysfunction and multiorgan damage." (PMID 40416618, 2025). "The inflammatory process was associated with increased endothelial dysfunction marker CD146 and Vascular cell adhesion marker 1(VCAM1) mRNA levels and CD146 protein expression, compared to sham mice, and this effect was significantly more pronounced in WTGal−3−/−BM mice, 48 h and 28d after rIR." (PMID 41285927, 2025). "Several studies indicate that ASD patients exhibit increased levels of VCAM-1, suggesting endothelial dysfunction and enhanced leukocyte infiltration into the brain, which may have adverse bearing on synaptic plasticity, axon growth, and repulsion." (PMID 41300606, 2025). "VCAM-1, by contrast, is important in leukocyte adhesion and the pathogenesis of vascular inflammation with a resultant contribution to diabetic atherosclerosis and endothelial dysfunction." (PMID 41099986, 2025). "Furthermore, the increased expression of surface proteins that indicate endothelial dysfunction includes E-selectin, vascular cell adhesion molecule 1 (VCAM-1), and ICAM-1." (PMID 39727939, 2024). "Reduction of VCAM-1 gene expression can reduce vascular inflammation and endothelial dysfunction." (PMID 38195507, 2024). "The first step in atherogenesis involves endothelial dysfunction, characterized by increased permeability, decreased nitric oxide (NO) production, and enhanced expression of adhesion molecules, such as vascular cell adhesion molecule-1 (VCAM-1) and intercellular adhesion molecule-1 (ICAM-1)." (PMID 39596083, 2024). "VCAM-1 is involved in inflammation and progress, thereby contributing to endothelial dysfunction." (PMID 38195507, 2024).